RN7SKP58 (RN7SK pseudogene 58)
Gene: Miscellaneous RNA gene on chromosome 3 (41,766,615 to 41,766,919, reverse strand). Ensembl gene ENSG00000222942.
Homologues: Orthologues: chimpanzee 7SK (99% identical), mouse Gm55029 (52% identical), mouse Gm56292 (49% identical). Paralogues in human: RN7SKP59 (77% identical), RN7SKP255 (71% identical), RN7SKP79 (70% identical), RN7SKP71 (69% identical), RN7SKP95 (69% identical), RN7SKP146 (69% identical), RN7SKP163 (69% identical), RN7SKP171 (69% identical), RN7SKP9 (69% identical), RN7SKP202 (69% identical), RN7SKP47 (69% identical), RN7SKP86 (69% identical), and 284 more.